TIMM9 (translocase of inner mitochondrial membrane 9)
Description:
Mitochondrial intermembrane chaperone that participates in the import and insertion of multi-pass transmembrane proteins into the mitochondrial inner membrane. May also be required for the transfer of beta-barrel precursors from the TOM complex to the sorting and assembly machinery (SAM complex) of the outer membrane. Acts as a chaperone-like protein that protects the hydrophobic precursors from aggregation and guide them through the mitochondrial intermembrane space.
Synonyms: TIM9; TIM9A
Tractability: Small molecule: a structure with a bound ligand is known. Antibody: UniProt places it where antibodies can reach, with high confidence. PROTAC: ubiquitination databases record sites on it; its protein half-life has been measured.
Gene: Protein-coding gene on chromosome 14 (58,407,461 to 58,427,655, reverse strand). Ensembl gene ENSG00000100575.
Subcellular location: Mitochondrion inner membrane
Subcellular location (Human Protein Atlas): Mitochondria
Pathways (Reactome):
Metabolism of proteins: Mitochondrial protein degradation
Protein localization: Mitochondrial protein import
Gene Ontology:
Molecular function: protein binding; protein homodimerization activity; protein-folding chaperone binding; protein transporter activity; zinc ion binding
Biological process: protein insertion into mitochondrial inner membrane
Cellular component: mitochondrial inner membrane; mitochondrial intermembrane space; mitochondrial intermembrane space chaperone complex; mitochondrion; TIM22 mitochondrial import inner membrane insertion complex
Genetic constraint (gnomAD): Loss-of-function variants: 7 observed, 10.83 expected, observed/expected ratio (o/e) 0.65, 90% interval 0.37 to 1.21. The upper end of that interval is the gene's LOEUF score, 1.21, which puts it in group 5 of 6, group 1 being the genes least tolerant of losing a copy. Missense variants: 74 observed, 91.08 expected, observed/expected ratio (o/e) 0.81, 90% interval 0.67 to 0.99. Synonymous variants: 28 observed, 28.67 expected, observed/expected ratio (o/e) 0.98, 90% interval 0.72 to 1.34.
Homologues: Orthologues: chimpanzee TIMM9 (100% identical), dog TIMM9 (99% identical), rabbit TIMM9 (99% identical), rat Timm9 (99% identical), mouse Timm9 (98% identical), guinea pig TIMM9 (97% identical), zebrafish timm9 (92% identical), Drosophila melanogaster Tim9a (51% identical), Caenorhabditis elegans tin-9.1 (36% identical).
Diseases named in the same sentence as TIMM9 in open-access papers:
TIMM9 is named in the same sentence as 10 diseases in open-access papers, as found by Europe PMC text mining. Sharing a sentence is not in itself a finding about the gene and the disease. The quoted sentences say what the papers report.
hepatocellular carcinoma (2 papers, 2022 to 2023). A malignant tumor that arises from hepatocytes. "ABCB6, IPO7, TIMM9, FZD7, and ACAT1, the five HBV-related genes that affect the prognosis, can work as reliable biomarkers for the diagnosis of Hepatocellular carcinoma, giving a new insight for improving the prognosis, diagnosis, and treatment outcomes of HBV-type Hepatocellular carcinoma." (PMID 36685852, 2022).
diabetes (1 paper, 2022). "Mitochondria-related genes, such as ATP5C1 and TIMM9, promote mitochondrial biogenesis, which is beneficial for the treatment of diabetes." (PMID 35445133, 2022).
gastric cancer (1 paper, 2022). A primary or metastatic malignant neoplasm involving the stomach. "Overexpression of TIMM9 is associated with vascular invasion in gastric cancers and is inversely correlated with the survival of patients with gastric cancer, which indicates that TIMM9 can be used as a marker to predict the outcomes of patients with gastric cancer." (PMID 36105252, 2022).
glioma (1 paper, 2022). A benign or malignant brain and spinal cord tumor that arises from glial cells (astrocytes, oligodendrocytes, ependymal cells). "MRE11, RTCB, TIMM9 and METTL14 were up‐regulated in gliomas, while CDPIT and MFN2 were down‐regulated." (PMID 35044082, 2022).
liver cancer (1 paper, 2023). An epithelial or non-epithelial malignant neoplasm that arises from the liver. "TIMM9 is a mitochondrial protein whose expression is increased in various cancers, including thyroid, lung and liver cancer." (PMID 37143953, 2023).
mesothelioma (1 paper, 2023). A usually malignant and aggressive neoplasm of the mesothelium which is often associated with exposure to asbestos. "Other highly expressed genes in sarcomatoid mesothelioma cell lines were two ATP synthase subunits (ATP5H, ATPO), MTCO2, COX5B, COX 6C2, IDH3A, IDH3B and TIMM9." (PMID 37297007, 2023).
psoriasis (1 paper, 2022). An autoimmune condition characterized by red, well-delineated plaques with silvery scales that are usually on the extensor surfaces and scalp. "For immune cells, T cells and Monocytes were related to PEBP1, MDM2, TIMM9 and DCAF7 in psoriasis group." (PMID 36685512, 2022). "Typically, CISD1 (p = 3.9e-10), TRIB2 (p < 2.22e−16), and ABCC5 (p=0.0012) levels among psoriasis cases increased compared with healthy controls, whereas PRKAA2 (p < 2.22e−16), ACSF2 (p = 3e−15), TIMM9 (p= 0.049), PEBP1 (p < 2.22e−16) and NR5A2 (p=1.8e−13) levels decreased among psoriasis cases." (PMID 36685512, 2022).
tumor (3 papers, 2022 to 2023). "A heatmap between normal and tumor tissues showed the expression of G6PD, HRAS, NRAS, TIMM9, and MYCN." (PMID 37143953, 2023). "In our study, TIMM9 expression was also elevated in HCC tumor samples compared to nontumor liver samples." (PMID 36105252, 2022). "Therefore, this study was the first proposed the relationship between ABCB6, IPO7, TIMM9, and ACAT1 and HBV, and they may be related to tumor progression in HBV-induced HCC as FZD7." (PMID 36685852, 2022).
cancer (2 papers, 2022 to 2023). A tumor composed of atypical neoplastic, often pleomorphic cells that invade other tissues. "TIMM9 is a mitochondrial protein that is expressed in various cancer cells depending on the cancer type." (PMID 36105252, 2022).
TIMM9 also shares sentences with these, for which no sentence is quoted: breast carcinoma (1 paper).